PDGFRA (platelet derived growth factor receptor alpha)
Diseases named in the same sentence as PDGFRA in open-access papers (continued):
Sharing a sentence is not in itself a finding about the gene and the disease.
glioblastoma (continued). "In this study, we correlated glioblastoma locations with the expression of five mesenchymal genes (VEGFC and its receptor FLT4, HGF and its receptor MET, and CHI3L1) and five proneural genes (PROM1, NOTCH1, DLL3, PDGFRA, and BCAN)." (PMID 26637806, 2016). "Similarly, we detected heterogeneity of PDGFRA amplification within BI06, an IDH1-mutant glioblastoma." (PMID 25608559, 2014). "In our hands, amplification of any of PDGFRA, KIT or VEGFR2 is found in nearly a quarter of glioblastoma cases, with individual genes ranging from 14–25%, which may itself be an underestimate due to sampling." (PMID 23990986, 2013). "The poor efficacy of single treatments may be explained by concurrent activation of multiple RTKs in glioblastoma, including EGFR, ERBB2, PDGFRA and MET." (PMID 23874926, 2013). "Notably, both PDGFRα and EGFR genes are frequently over-amplified in glioblastoma, which may facilitate the virus’s entry into glioblastoma cells." (PMID 41194660, 2025). "PDGFRA amplification or expression was not correlated with the outcomes of glioblastoma (GBM)." (PMID 36043552, 2023). "Low-dose radiation stimulates GBM cells to secrete circ-METRN-rich SEVs, and circ-METRN enhances glioblastoma progression and radioresistance by regulating the miR-4709-3p/GRB14/PDGFRα pathway." (PMID 35999601, 2022). "Our finding of simultaneous amplification of PDGFRA and MET in a subset of DIPG, for example, may justify the use of multikinase inhibitors or combinations of TKI, as has been demonstrated for pediatric glioblastoma cells in vitro." (PMID 22389665, 2012). "Despite significant drug concentrations reached inside the glioblastoma, imatinib has shown limited efficacy in recurrent or newly diagnosed glioblastoma in adults and response to the drug was not increased in patients with PDGFRA immunopositivity." (PMID 22389665, 2012). "Glioblastoma multiforme (GBM) is an aggressive primary brain cancer that includes focal amplification of PDGFRα and for which there are no effective therapies." (PMID 30082792, 2018). "Two anti-PDGFRα monoclonal antibodies, olaratumab (NCT00895180) and tovetumab, have been trialled in recurrent glioblastoma patients, but neither showed significant clinical activity." (PMID 37857607, 2023). "EGFR, Integrin αvβ3, Neuropilin-2, and PDGFRα, but not CD90 and CD147, were significantly upregulated in glioblastoma than normal brain tissues by GEPIA analysis." (PMID 37146061, 2023). "PDGFR inhibition in GBM cell lines universally triggers a G2/M arrest and in a PDGFRA/PDGFA driven glioblastoma mouse model chronic activation of PDGFRA facilitates microtubule dynamics during mitosis, suggesting a role for PDGFR in driving GBM cells towards mitosis." (PMID 33478100, 2021). "Among primary glioblastomas of the proneural non-CpG island methylation (non G-CIMP) subtype, PDGFRA amplifications even reach a frequency of greater than 50%1." (PMID 25683249, 2015).
eosinophilia (85 papers, 2009 to 2026). "Both the World Health Organization (WHO) and the International Consensus Classification (ICC) have updated the former category of “Myeloid/Lymphoid Neoplasms Associated with Eosinophilia and Rearrangement of PDGFRA, PDGFRB, FGFR1, or PCM1::JAK2”." (PMID 41530508, 2026). "Eosinophilia can be a feature of certain malignancies, particularly myeloproliferative neoplasms associated with platelet-derived growth factor receptor alpha (PDGFRA)." (PMID 40534692, 2025). "It consists of a distinct disease from myeloid/lymphoid neoplasms associated with eosinophilia and rearrangement of PDGFRA, PDGFRB, or FGFR1, or with PCM1-JAK2." (PMID 34441019, 2021). "Myeloid neoplasms with prominent eosinophilia often have rearrangements in the platelet-derived growth factor receptor α (PDGFRA) or β (PDGFRB) or are associated with core-binding factor AML." (PMID 34285820, 2021). "The category of myeloid/lymphoid neoplasms with eosinophilia and rearrangement of PDGFRA, PDGFRB, FGFR1 and PCM1-JAK2 represents an uncommon cause of eosinophilic lung infiltrate." (PMID 31744552, 2019). "A distinct classification of myeloid and lymphoid neoplasms associated with eosinophilia and rearrangements of PDGFRA, PDGFRB, FGFR1 or with a PCM1-JAK2 rearrangement is described in the WHO 2017." (PMID 30696948, 2019). "A conclusive diagnosis of myeloid/lymphoid neoplasm with eosinophilia associated with PDGFRA rearrangement was rendered." (PMID 31744552, 2019). "Hematologic malignancies associated with PDGFRA rearrangement commonly manifest as myeloid or lymphoid neoplasms with eosinophilia." (PMID 29541391, 2018). "As the spectrum of malignancies associated with this rearrangement expanded, the 2008 WHO classification developed a category for these neoplasms, “Myeloid and lymphoid neoplasms associated with eosinophilia and abnormalities of PDGFRA, PDGFRB, or FGFR1 ”." (PMID 26457233, 2015). "Clonal eosinophilia is classified into two categories depending on whether there is a molecular rearrangement of the PDGFRA, PDGFRB, or FGFR1 genes, which are responsible for encoding the tyrosine kinase receptors that aid in eosinophil growth." (PMID 39301376, 2024). "In the context of FIP1L1-PDGFRA-positive MPN with eosinophilia, the concurrent PTPN11 mutation could have amplified downstream signaling, making the leukemic cells less dependent on PDGFRA-driven pathways and more resistant to tyrosine kinase inhibitors like imatinib." (PMID 40141849, 2025). "The frequency of eosinophilia varied significantly depending on the specific fusion gene involved: it was present in 91% of patients with FIP1L1::PDGFRA and 100% with ETV6::ABL1, but only in 43% of those with PDGFRB, FGFR1, or JAK2 fusion genes." (PMID 41530508, 2026). "Due to the worsening thrombocytopenia and persistent eosinophilia, it was decided that the patient would undergo a bone marrow biopsy within the next week to further characterize any abnormalities in the PDGFRA, PDGFRB, FGFR1, and PCM1-JAK2 genes." (PMID 40144421, 2025). "It falls under the category of myeloid/lymphoid neoplasms with eosinophilia and rearrangements involving PDGFRA, PDGFRB, FGFR1, or PCM1-JAK2, as classified in the 2016 World Health Organization classification of myeloid neoplasms." (PMID 40141849, 2025). "Myeloid (and lymphoid) neoplasms with eosinophilia are associated with rearrangement of the tyrosine kinase (TK) genes, namely PDGFRB, PDGFRA, FGFR1, JAK2, FLT3, and ABL1 (excluding BCR-ABL1)." (PMID 39156600, 2024). "Myeloid or lymphoid neoplasms with eosinophilia can demonstrate gene rearrangements in PDGFRA, PDGFRB, FGFR1, JAK2, or FLT3 or ETV6::ABL or other tyrosine kinase gene fusion (MLN-TK)." (PMID 38611061, 2024). "Recognizing AML with eosinophilia due to PDGFRA and PDGFRΒ rearrangement is important, because the aberrant tyrosine kinase activity can make the disease responsive to tyrosine kinase inhibitors such as imatinib." (PMID 38337573, 2024).
eosinophilia (continued). "Eosinophilia is the dominant feature of blood cell analysis in CEL and the most frequent PDGFRA-associated MLN-TK." (PMID 37274287, 2023). "For example, most patients with the FIP1L1::PDGFRA fusion gene present with a chronic myeloid neoplasm with eosinophilia; however, mixed lineage presentations are more common in patients with FGFR1 fusions." (PMID 37076693, 2023). "“Myeloid/lymphoid neoplasm with eosinophilia (M/LNs‐Eo) and rearrangement of PDGFRA, PDGFRB or FGFR1, or with PCM1‐JAK2” is recognized as a specific diagnostic category in the 2017 World Health Organization (WHO) classification." (PMID 36051048, 2022). "Crucial differential diagnoses of Ph− MPN are the category of myeloid/lymphoid neoplasms with eosinophilia and gene rearrangement of PDGFRA, PDGFRB or FGFR1, or with PCM1-JAK2, and myelodysplastic/myeloproliferative neoplasms (MDS/MPN)." (PMID 34298741, 2021). "The present challenging case of eosinophilia clarifies the progressive workup, which led to the diagnosis of myeloid/lymphoid neoplasm with eosinophilia and rearrangement of PDGFRA, a rare disease with less than 1 case per 1000000 persons per year." (PMID 31744552, 2019). "A thorough step-wise patient’s evaluation led to identify the clonal nature of eosinophilia and the diagnosis of myeloid/lymphoid neoplasm with eosinophilia and rearrangement of PDGFRA was made." (PMID 31744552, 2019). "In the present case the PDGFRA-rearranged neoplasm sustaining eosinophilia was effectively treated with imatinib with complete remission." (PMID 31744552, 2019). "Atypical mast cell proliferations or aggregates have been reported in myeloid neoplasms with prominent eosinophilia and abnormalities of PDGFRA or PDGFRB." (PMID 27648315, 2016). "For this reason, the 2008 WHO Classification of hematopietic and lymphoid tumors has introduced a separate diagnostic category for such disorders, referred to as “Myeloid and Lymphoid Neoplasms with Eosinophilia and Abnormalities of PDGFRα, PDGFRβ or FGFR1”." (PMID 26943776, 2016). "Previously it has been found that mast cells harbor PDGFRA rearrangements in cases of myeloid and lymphoid neoplasms with eosinophilia and abnormalities in PDFGRA, PDGFRB, or FGFR1." (PMID 27648315, 2016). "Based on these findings a diagnosis of myelodysplastic/myeloproliferative neoplasm with eosinophilia and PDGFRA rearrangement was rendered." (PMID 24669761, 2014). "A separate category has been made for myeloid and lymphoid neoplasms with eosinophilia and abnormalities of PDGFRA, PDGFRB, or FGFR1." (PMID 24764730, 2014). "Myeloproliferative neoplasm with eosinophilia and platelet-derived growth factor receptor-alpha gene and Fip1-like 1 gene mutation (FIP1L1-PDGFRA; F/P) is a low-burden disease with dramatic response to imatinib therapy." (PMID 24764730, 2014). "The unexpected and abrupt presence of prominent eosinophilia in the peripheral blood and bone marrow at this point in time prompted us to evaluate for PDGFRA rearrangement." (PMID 24669761, 2014). "PDGFRA-positive myeloid neoplasm with eosinophilia is a rare disease and this study indicates the need to do the PDGFRA assay in patients with HES." (PMID 24764730, 2014). "Our case highlights the importance of assessing for PDGFRA rearrangement in myeloid neoplasms with de novo or subsequently acquired eosinophilia." (PMID 24669761, 2014). "In 2008, a new class of hematopoietic system disorders, myeloid and lymphoid neoplasms with eosinophilia and abnormalities in PDGFRA, PDGFRB and FGFR1 genes, was created by WHO." (PMID 22356850, 2012). "In 2008 WHO classification, a new class of hematopoietic diseases, myeloid and lymphoid neoplasms with eosinophilia and abnormalities in PDGFRA, PDGFRB and FGFR1 genes, were introduced." (PMID 22356850, 2012).
eosinophilia (continued). "Additionally, PDGFRA rearrangements have been increasingly described in myeloid neoplasms with eosinophilia, further supporting a mechanistic relationship between this signaling pathway and the eosinophil-rich stroma characteristic of IFPs." (PMID 41562800, 2025). "Still, the prior exclusion of FIP1L1::PDGFRA positive cases by RT‐PCR might be advised to reduce costs and to reserve the analysis for patients with persisting, unexplained eosinophilia and related organ damage." (PMID 40533930, 2025). "Besides eosinophilia, patients often present with monocytosis and an elevated serum tryptase, particularly in cases with PDGFRA or PDGFRB fusion genes." (PMID 39037514, 2024). "Eosinophilia is present in almost all cases of MLN-TK, caused by fusion genes involving a receptor [PDGFRA or B, fibroblast growth factor receptor (FGFR), fms like tyrosine kinase 3 (FLT3)], a transcription factor (ETV-6), or a non-receptor kinase (Janus kinase 2, JAK2)." (PMID 37274287, 2023). "This category name has changed from the previous “myeloid/lymphoid neoplasms with eosinophilia and rearrangement of PDGFRA, PDGFRB or FGFR1, or with PCM1::JAK2” (MLN-eo), to specify the underlying molecular genetic changes and to include cases with ETV6::ABL1, FLT3 fusions or other TK fusion genes." (PMID 37454239, 2023). "Myeloid/lymphoid neoplasm with eosinophilia was excluded due to the absence of eosinophilia and lack of mutations in PDGFRA, PDGFRB, FGFR1, or PCM1-JAK2 gene rearrangement." (PMID 35228982, 2022). "Thus, the final diagnosis was B-cell lymphoblastic lymphoma arising in the setting of myeloid/lymphoid neoplasm with eosinophilia and PDGFRA rearrangement." (PMID 36589160, 2022). "However, to date, only imatinib has been approved as a first-line treatment for patients with myeloid disease, with eosinophilia expressing FIP1L1-PDGFRα or carrying other PDGFRα or PDGFRβ fusions." (PMID 33418988, 2021). "Similarly, c-Kit expression on gastrointestinal stromal tumours (GIST) renders these tumours sensitive to imatinib as are the rare cases of mastocytosis with eosinophilia due to PDGFRA expression or mutant c-Kit expression." (PMID 31035962, 2019). "Evidence about genetic mutations/rearrangements causing eosinophil expansion is maturing with the recognition of a new specific World Health Organization category, named “Myeloid/lymphoid neoplasms with eosinophilia and rearrangement of PDGFRA, PDGFRB, or FGFR1, or with PCM1-JAK2”." (PMID 29619379, 2018). "Cases of AML with PDGFRA, PDGFRΒ, and FGFR1 rearrangements are included in the current WHO classification in the broad category of “myeloid/lymphoid neoplasms with eosinophilia and tyrosine kinase gene fusions”." (PMID 38337573, 2024). "In the case of eosinophilia, FISH/cytogenetics and molecular analysis (on bone marrow aspirate or peripheral blood cells) should specifically look for PDGFRA, PDGFRB, FGFR1, FLT3, ETV6, and JAK2 gene rearrangements." (PMID 37274287, 2023). "The diagnosis of myeloid neoplasm with eosinophilia and rearrangement of PDGFRA was made following confirmation by fluorescence in situ hybridization (FISH) test for FIP1L1-PDGFRA gene fusion." (PMID 36589160, 2022). "We tested the FIP1L1/PDGFRA and BCR/ABL fusion genes to exclude the possibility of a myeloid neoplasm or clonal eosinophilia." (PMID 33916211, 2021). "Among the alterations found in primary Eosinophilia, gene fusions involving PDGFRα, PDGFRβ, FGFR1 or JAK2 represent the biomarkers of WHO-defined "myeloid and lymphoid neoplasms with eosinophilia"." (PMID 34772467, 2021). "Myeloid neoplasm with eosinophilia and FIP1-like-1-platelet-derived growth factor receptor-alpha (FIP1L1-PDGFRA) rearrangement is a multi-organ disease with diverse clinical presentation." (PMID 31737382, 2019). "Therefore, we suggest that molecular genetic analysis (FISH and RT-PCR) for PDGFRA and PDGFRΒ should be carried out in cases of AML with peripheral eosinophilia." (PMID 38337573, 2024).
eosinophilia (continued). "While patients with PDGFRA and PDGFRB fusion genes, who are receiving imatinib treatment, generally have a favorable prognosis, the advent of FGFR1 inhibitors offers hope for individuals with clonal eosinophilia and FGFR1 fusion genes." (PMID 39037514, 2024). "FIP1L1::PDGFRA and ETV6::ABL1 fusion genes share striking clinical and morphological similarities including male predominance, the relative frequency of eosinophilia and monocytosis, the median absolute number of eosinophils, and presentation or progression to BP including EMD." (PMID 37454239, 2023). "The incidence has been reported to be 0.036/100,000 for HES in the USA and 0.018/100,000 specifically diagnosed with the most prevalent primary eosinophilia, a factor interacting with PAPOLA and CPSF1-platelet-derived growth factor receptor alpha (FIP1L1-PDGFRA)-positive neoplasms, in France." (PMID 37274287, 2023). "Unlike the case with PDGFRA/B-rearranged myeloid/lymphoid neoplasms with eosinophilia, imatinib therapy is ineffective in CEL-NOS." (PMID 29426921, 2018). "Such TKFs characterize a group of hematological disorders, sharing similar clinico-pathological features, such as peripheral blood eosinophilia, clinical presentation as MPN and/or lymphoid tumors, and, at least for PDGFRα and PDGFRβ fusions, good response to Imatinib." (PMID 26943776, 2016). "After ruling out the hypothesis of non−hematologic origin, testing for gene rearrangements associated with clonal eosinophilia, such as BCR::ABL1, PDGFRA, PDGFRB, FGFR1, PCM1::JAK2, and JAK2::V617F, did not yield any definitive clues." (PMID 38992589, 2024). "If either PDGFRA, PDGFRB, FGFR1, or JAK2::PCM1 gene rearrangement is identified, the diagnosis should be classified as “myeloid or lymphoid neoplasms with eosinophilia and tyrosine kinase gene fusions”; eosinophilia may be a clue to this alternative diagnosis." (PMID 38067330, 2023). "The other samples belonged to patients with MLN with a PDGFRα rearrangement (1 case), lymphoid neoplasms (5 cases: 1 ALL, 1 CLL, 1 hairy cell leukemia, and 2 NHL), or reactive disorders/non-conclusive final diagnoses (75 cases of thrombosis, polycythemia, eosinophilia, anemia)." (PMID 30785480, 2019). "Rearrangements of the platelet-derived growth factor receptor alpha (PDGFRA) gene, of the platelet-derived growth factor receptor beta (PDGFRB) gene and the fibroblast growth factor receptor 1 (FGR1) gene or PCM1-JAK2 fusions must be excluded if eosinophilia is present." (PMID 29383443, 2018). "Clonal eosinophilia is associated with myeloid or lymphoid neoplasms harboring PDGFRA, PDGFRB, or FGFR1 rearrangements, Philadelphia-negative myeloproliferative neoplasms, acute myeloid leukaemia, and B- or T-lymphoblastic leukemia/lymphoma featuring marked eosinophilia." (PMID 41552084, 2025). "Fip1-like 1-platelet-derived growth factor receptor alpha and platelet-derived growth factor receptor beta 5q33 translocations, which are genetic abnormalities indicative of myeloproliferation, were negative in this case; moreover, no findings of neoplastic eosinophilia were observed." (PMID 37543825, 2023). "Nearly 100 different TK fusion genes, involving at least six TK (PDGFRA, PDGFRB, FGFR1, JAK2, ABL1, FLT3), have been identified in distinct MLN with or without eosinophilia." (PMID 39037514, 2024). "To date, more than 70 different TK fusion genes with recurrent involvement of at least six TK (PDGFRA, PDGFRB, FGFR1, JAK2, ABL1, FLT3) have been identified in clinically and morphologically distinct MLN with or without eosinophilia." (PMID 37454239, 2023). "Unlike other rearrangements of PDGFRA, the clinical manifestations of BCR-PDGFRA rearrangement are resembling CML without eosinophilia increase." (PMID 35713428, 2022).
eosinophilia (continued). "Herein, we report the case of a 73-year-old male with acute myeloid leukemia arising from MDS, negative for PDGFRA and PDGFRB, positive for bone marrow eosinophilia, rash, and marked fluid retention, which improved dramatically with imatinib therapy." (PMID 27570624, 2016). "A case series from Germany described five patients with FIP1L1- PDGFRA who presented with AML and eosinophilia, but no history of antecedent myeloid malignancy was reported for any of the patients." (PMID 24669761, 2014). "In 81/135 (60%) evaluable patients, hypereosinophilia (>1.5 × 109/l) was observed in 40/44 (91%) FIP1L1::PDGFRA and 7/7 (100%) ETV6::ABL1 positive patients but only in 13/30 (43%) patients with PDGFRB, FGFR1, and JAK2 fusion genes while 9/30 (30%) patients had no eosinophilia." (PMID 37454239, 2023).